FABP4 (fatty acid binding protein 4)
Diseases named in the same sentence as FABP4 in open-access papers (continued):
Sharing a sentence is not in itself a finding about the gene and the disease.
Insulin resistance (continued). "Despite the upregulation of genes involved in fatty acid synthesis (Fasn and Scd-1) and fatty acid uptake (Fabp1 and Fabp4), cadmium exposure did not lead to insulin resistance or hepatic lipid accumulation, and instead, it improved glucose tolerance." (PMID 39839416, 2024). "Obese mice deficient in both FABP4 and FABP5 had reduced storage of fatty acids in adipose tissue and no insulin resistance." (PMID 37794302, 2024). "LBW combined with high-fat diets may increase insulin resistance and diabetes through regulating the CD36-related Fabp4-PPARγ and AMPK/ACC signaling pathways." (PMID 34983495, 2022). "FABP4/FABP5 genes (fatty acid binding proteins 4 and 5) are directly involved in the regulation of fat deposition, are mainly expressed in fat and bone marrow cells, and are related to the development of insulin resistance." (PMID 34419151, 2021). "Among the FABPs, fatty acid-binding protein 4 (FABP4) is mainly expressed in adipocytes and macrophages and plays a vital role in the pathogenesis of insulin resistance and type 2 diabetes, indicating that it might also have predictive value for GDM." (PMID 34368366, 2021). "Among FABPs, FABP4, also known as aP2 or adipocyte FABP, is mainly expressed in adipocytes and macrophages and is related to the development of metabolic disorders including insulin resistance and atherosclerosis." (PMID 33071982, 2020). "Among FABPs, fatty acid binding protein 4 (FABP4), also referred to as adipocyte FABP or aP2, is mainly expressed in adipose tissue, including adipocytes and macrophages, and plays an important role in the development of insulin resistance and atherosclerosis." (PMID 32539832, 2020). "Lipolysis-associated secretion of FABP4 from adipocytes is caused by a non-classical secretion pathway despite the lack of signal peptides, and secreted FABP4 has effects as an adipokine on insulin resistance, atherosclerosis and vascular remodeling." (PMID 33071982, 2020). "FABP4 appears to be one of the most probable candidates involved in the pathophysiology of GDM, as well as adiposity, insulin resistance, type 2 diabetes mellitus (T2DM), atherosclerosis, hypertension, coronary artery, cerebrovascular diseases, and metabolic syndrome." (PMID 30818771, 2019). "The study subject was FABP4—a newer adipokine which appears to be involved in the pathophysiology not only of GDM but also of adiposity, insulin resistance, T2DM, atherosclerosis, hypertension, coronary artery and cerebrovascular diseases, and metabolic syndrome." (PMID 30818771, 2019). "The elevated plasma FABP4 level is a negative prognostic factor, correlated with metabolic syndrome, insulin resistance (calculated as HOMA-IR), and mortality of patients with advanced hepatic cirrhosis and sepsis." (PMID 29849871, 2018). "To date, the mechanism by which FABP4 promotes insulin resistance, inflammation or pulmonary dysfunction are not fully understood." (PMID 26887419, 2016). "FA binding protein 4 (FABP4) and FABP5, which are abundantly expressed in adipose tissues and macrophages, have been identified as key molecules in the pathogenesis of overnutrition-related diseases, such as insulin resistance and atherosclerosis." (PMID 24603714, 2014). "It has also been demonstrated that secretion of FABP4 is via a non-classical secretion pathway and that FABP4 acts as an adipokine for the development of hepatic insulin resistance." (PMID 25142635, 2014). "In contrast, a recent study showed that FABP4/5 inhibitors ameliorate dyslipidaemia but not insulin resistance in diet-induced obese mice." (PMID 22709426, 2012). "Moreover, hepatic insulin resistance, assessed by HOMA-IR, may lead to fasting hyperglucagonaemia, and HOMA-IR was also paralleled by increased serum FABP4 levels." (PMID 34174950, 2021).
Insulin resistance (continued). "Fatty acid–binding protein 4 (FABP4), also known as adipocyte FABP (A-FABP) or aP2, is mainly expressed in adipocytes and macrophages and plays an important role in the development of insulin resistance and atherosclerosis following metaflammation (low-grade and chronic inflammation)." (PMID 32075656, 2020). "For example, there is suggested to be a component of insulin resistance in neurodegeneration and lesion formation that may be influenced by FABP4, which could not be addressed by an Ab-based therapy." (PMID 30705117, 2019). "Fatty acid-binding protein 4 (FABP4), known as adipocyte FABP (A-FABP) or aP2, and FABP5, known as epidermal FABP (E-FABP) or mal1, are expressed in both adipocytes and macrophages and play an important role in the development of insulin resistance and atherosclerosis." (PMID 27936164, 2016). "Besides, fatty acid‐binding protein 4 (FABP4 or aP2) which is mainly expressed in adipocytes and macrophages also plays an important role in lipolysis for transportation of fatty acids and in the development of insulin resistance and atherosclerosis in relation to meta inflammation." (PMID 28816006, 2018). "We found the strongest negative correlation between FABP4 and GDR compared with the other markers connected to insulin resistance or body composition." (PMID 28654680, 2017). "Fourth, some diabetes markers, such as Homeostatic Model Assessment of Insulin Resistance (HOMA-IR) and Hemoglobin A1c (HbA1c) might affect the predictive effectiveness of FABP4 in the non-diabetic patients." (PMID 30969942, 2019). "Similarly, C3H mice, which lack Pparγ expression in the liver, did not enhance hepatic Cd36, Fabp4, and Mogat1 expression on the SRD diet or in response to liver insulin perfusions, and furthermore, they did not develop hepatosteatosis and hepatic insulin resistance in response to the SRD." (PMID 26085100, 2015).
atherosclerosis (205 papers, 2010 to 2025). A disease characterized by the build-up of fatty material and calcium deposition in the arterial wall resulting in partial or complete occlusion of the arterial lumen. "Patients with CAS displayed an upregulation of FABP4 gene expression that encodes fatty acid binding protein 4, which is involved in macrophage activation and lipid metabolism in atherosclerosis." (PMID 41410816, 2025). "FABP4 mRNA is associated with atherosclerosis status in patients who underwent coronary bypass surgery." (PMID 37794302, 2024). "FABP4 activation has been linked to atherosclerosis, coronary artery disease, and heart failure due to its involvement in angiogenesis." (PMID 37794302, 2024). "A previous study reported that high levels of FABP4 contribute to elevated blood pressure, which is another risk factor for atherosclerosis." (PMID 38731797, 2024). "Studies in FABP4-deficient mice have shown that this lipid chaperone has a significant role in several aspects of metabolic syndrome, including type 2 diabetes and atherosclerosis." (PMID 38751858, 2024). "We identified 15 identical pathogenic genes, and four of which (MMP9, MMP12, CD36, and FABP4) were considered as the key target genes of atorvastatin in anti-atherosclerosis and NSCLC." (PMID 37978381, 2023). "Apolipoprotein E-deficient mice null for FABP4 shows reduced atherosclerotic lesions and improved atherosclerosis and survival." (PMID 36769659, 2023). "FABP4 plays an important role in macrophage inflammation and lipid metabolism in atherosclerosis, and serum FABP4 is strongly associated with cardiovascular disease mortality." (PMID 36532833, 2022). "It has been further reported that FABP4 is associated with atherosclerosis and cardiovascular diseases." (PMID 36311201, 2022). "Further, FABP4-deficient macrophages in atherosclerosis show a significantly declined appearance of inflammatory cytokines." (PMID 36432506, 2022). "Fatty acid-binding protein 4 (FABP4) is well known for its pathogenic effect in metabolic diseases such as atherosclerosis and diabetes mellitus." (PMID 35410456, 2022). "In the cardiovascular system, FABP4 has been demonstrated to cause pressure overload-induced cardiac hypertrophy 21; and can be therapeutically targeted against severe atherosclerosis." (PMID 32724455, 2020). "Atherosclerosis caused significant increases in the FABP4 mRNA level (+94.4%, p <0.05) in human myocardium." (PMID 31979197, 2020). "Studies in humans have shown that a genetic variant at the FABP4 locus reduced the risk for atherosclerosis, diabetes and coronary heart disease, and reduced FABP4 expression in adipose tissue was related to lower risk for CAD and DM." (PMID 27864793, 2017). "The pharmacological inhibition of Fabp4 significantly protected against atherosclerotic plaque formation in the ApoE-deficient animal model of atherosclerosis." (PMID 29064389, 2017). "FABP4-deficient mice showed protection from atherosclerosis and FABP4-deficient macrophages influenced the production of inflammatory cytokines." (PMID 26823558, 2016). "Peritoneal macrophages of llee male mice have reduced mRNA expression of FABP4, a fatty acid binding protein implicated in atherosclerosis." (PMID 24489659, 2014). "In an Apoe−/− mouse model, macrophage deficiency of FABP4 leads to a strong protection against development of atherosclerosis." (PMID 24489659, 2014). "From an unbiased strategy, we identified cellular FABP4 expression in circulating leucocytes to be associated with the extent of atherosclerosis." (PMID 23387955, 2013). "The large decrease in Fapb4 is of particular interest in that Fabp4 deficient mice on an apoE–/– background show a striking protection from atherosclerosis." (PMID 22276189, 2012). "Bone marrow transplantation studies demonstrated that the protective effect of FABP4 deficiency on atherosclerosis is predominantly related to actions in macrophages rather than in adipocytes." (PMID 22121495, 2011).
atherosclerosis (continued). "FABP4 has been implicated as a therapeutic target for treating diabetes and atherosclerosis." (PMID 40748031, 2025). "FABP4-deficiency may protect against atherosclerosis in apolipoprotein E-deficient mice, and FABP4 knockout mice may have a reduced ability in accumulating cholesterol esters." (PMID 37274820, 2023). "Additionally, a basic experiment illustrated that FABP4 deficiency has a significant protective effect on atherosclerosis." (PMID 36060264, 2022). "FABP4 is a lipid carrier that is considered a key mediator of systemic metabolic and inflammatory processes and is closely associated with the development of metabolic syndrome, inflammation, and atherosclerosis." (PMID 36760798, 2022). "Macrophages are specific target cells for Fabp4 and its deficiency prevents atherosclerosis." (PMID 34834808, 2021). "FABP4 has also been associated with higher risk of atherosclerosis among adults." (PMID 34226637, 2021). "Furthermore, apolipoprotein E (Apoe)-deficient mice which also lack FABP4 are less prone to develop atherosclerosis than Apoe-deficient mice with FABP4." (PMID 34638803, 2021). "Therefore, given the multiple clinical associations, the direct causal role of FABP4 in clinical atherosclerosis requires further clarification." (PMID 33287461, 2020). "For the first time, it is possible to investigate previously perplexing questions regarding how deletion of FABP4 in distant tissues is implicated in the regulation of atherosclerosis formation, cancer progression, hepatic glucose production, and β-cell biology." (PMID 30705117, 2019). "Furthermore, the data from our group and other groups suggest that pharmacological inhibition of FABP4 should be explored as a potential therapeutic strategy for treating atherosclerosis and reducing cardiovascular risk." (PMID 24312381, 2013). "Furthermore, Fabp4−/−Fabp5−/− mice intercrossed into an ApoE-deficient atherosclerosis model developed dramatically less atherosclerosis than that in FABP4-deficient or wild-type mice on the same background." (PMID 22121495, 2011). "Similarly, CARMN might influence SMC functions by regulating metabolic pathways or inflammatory responses associated with FABP4, a protein active in lipid metabolism and inflammation, particularly in atherosclerosis and AAA." (PMID 38597937, 2024). "Therefore, since COPD is a disease with inflammation and high risk of atherosclerosis, plasma FABP4 levels may be closely related to COPD." (PMID 26823558, 2016). "FABP4 likely represents an important pathophysiological mediator of metabolic aberrations exerting a dramatic impact on obesity, insulin resistance, type 2 diabetes, fatty liver disease and atherosclerosis, all of which are conditions associated with the endocannabinoid system." (PMID 25485182, 2013). "Hundreds FABP4 inhibitors have been synthesized for effective atherosclerosis and diabetes treatments, including derivatives of niacin, quinoxaline, aryl-quinoline, bicyclic pyridine, urea, aromatic and other novel heterocyclic compounds." (PMID 40002815, 2025). "Studies have reported on various FABP4 inhibitors being synthesised for the treatment of diabetes and atherosclerosis, including derivatives of niacin, quinoxaline, aryl-quinoline, bicyclic pyridine, urea, aromatic compounds, and other heterocyclic compounds." (PMID 40234265, 2025). "Since FABP4 can be considered as a remarkable biomarker in patients with diabetes or atherosclerosis, it would be more meaningful to select periodontitis patients with systemic diseases to explore the linking biomarker of periodontitis and systemic diseases." (PMID 40002815, 2025). "Increased FABP4 level independently predicts atherosclerosis, evaluated by carotid intima-media thickness, a recognized marker of the disease." (PMID 40002815, 2025). "FABP4 has been linked to various components of metabolic syndrome in mice, including type 2 diabetes and atherosclerosis, and blocking FABP4 improved metabolism‐related issues." (PMID 40090836, 2025).
atherosclerosis (continued). "Future studies will investigate the changes in FABP4 markers and periodontal markers in patients with diabetes or atherosclerosis who also have periodontitis." (PMID 40002815, 2025). "Several specific FABP4 inhibitors have been synthesized, particularly for the treatment of type 2 diabetes and atherosclerosis." (PMID 37874427, 2024). "Foam cells on the inner membrane of the aorta in the atherosclerosis mice were significantly reduced in the presence of the FABP4 inhibitor (BMS309403, 25 mM)." (PMID 38751858, 2024). "Fatty acid binding protein 4 upregulates macrophage inflammation-related interleukin-6 (IL-6) level and regulates lipid metabolism in atherosclerosis induced by activation of the JAK2/STAT2 pathway." (PMID 38835896, 2024). "FABP-4 is correlated to atherosclerosis and heart failure, although less is known in patients with ConHD." (PMID 39711764, 2024). "Accordingly, in mouse models, genetic ablation, or pharmacological inhibition of FABP4 protects against atherosclerosis and type 2 diabetes by a mechanism involving PPARγ activation, which antagonizes NF-κB-dependent cytokine production." (PMID 37688656, 2024). "In this paper, we cover FABP4 biology, its implications in atherosclerosis from observational studies, genetic factors affecting FABP4 serum levels, and ongoing drug development to target FABP4 and offer insights into future FABP4 research." (PMID 38698167, 2024). "For example, genetic deletion of FABP4 not only protected mice against atherosclerosis, but also compromised the inflammatory response induced by macrophages, suggesting that FABP4 plays a critical role in peripheral macrophage-mediated inflammation." (PMID 37555918, 2023). "Other studies have shown that in mice with apolipoprotein E deficiency, FABP-4 gene deficiency protects these mice from atherosclerosis; therefore, FABP-4 inhibition effectively treats atherosclerosis in a mouse model." (PMID 38024104, 2023). "As a fatty acid transporter, FABP4 plays an important role in the uptake, transport, and metabolism of long-chain fatty acids and is closely related to atherosclerosis." (PMID 37978381, 2023). "In this study, FABP4 was highly expressed in atherosclerosis, which was consistent with existing reports." (PMID 37978381, 2023). "Taken together, these findings revealed the protective value of oridonin against atherosclerosis through FABP4/PPARγ pathway." (PMID 37905351, 2023). "In conclusion, the present study demonstrated that oridonin attenuated atherosclerosis by suppressing foam macrophage formation and inflammation through FABP4/PPARγ signalling pathway." (PMID 37905351, 2023). "The development of atherosclerosis and hypertension is accelerated by increased secretion of fatty acid-binding protein (FABP4) and retinol-binding protein (RBP-4)." (PMID 35456961, 2022). "One potential therapeutic strategy in the treatment of atherosclerosis or other cardiovascular diseases is the use of naphthalene-1-sulfonamide derivatives, which are selective FABP4 inhibitors." (PMID 35456961, 2022). "FABP4 pharmacological blockade has been shown to be effective for the treatment of atherosclerosis by modulating metabolic and inflammatory pathways." (PMID 35955575, 2022). "Initial studies demonstrated that fatty acid binding protein 4 (FABP4) mediates multiple physiological processes, including insulin sensitivity, attenuated atherosclerosis and inflammatory response 9-11." (PMID 35198079, 2022). "FABP4 and SREBP1 are implicated in regulating many metabolic pathways, such as those related to type 2 diabetes, atherosclerosis, and hepatic lipid accumulation." (PMID 34564583, 2021). "Mice with combined deficiency of FABP4 and FABP5 exhibited protection against type 2 diabetes, fatty liver disease and atherosclerosis more than did FABP4- or FABP5-deficient mice." (PMID 33597568, 2021).